AR (androgen receptor)
Diseases named in the same sentence as AR in open-access papers (continued):
Sharing a sentence is not in itself a finding about the gene and the disease.
prostate carcinoma (continued). "(i) Regulation of androgen receptors (AR): SIRT1 is able to modulate AR activity via direct deacetylation, leading to inhibition of AR activation, translocation and transcription of AR-dependent genes, for instance in prostate cancer." (PMID 33330467, 2020). "The new inhibitors displayed anti-proliferative effects in androgen-receptor positive prostate cancer cells that where further increased when combined with known inhibitors of related signaling pathways, such as PI3K, AKT and Androgen Receptor." (PMID 34458764, 2020). "The earlier study identified dysregulation of AR expression as the only shared event across all stages of prostate cancer." (PMID 32820253, 2020). "In order to study the significance of the AR-ESRP axis in prostate cancer, we employed an in vitro invasion assay." (PMID 32820253, 2020). "Previous studies showed that the androgen receptor (AR) pathway is a first-line therapeutic target for prostate cancer." (PMID 33292625, 2020). "It is known that the androgen receptor (AR) is a key driver of prostate cancer and inhibition of AR function by ADT is the mainstay of the current therapeutic strategy." (PMID 32244522, 2020). "Despite the clinical success of Androgen Receptor (AR)-targeted therapies, reactivation of AR signalling remains the main driver of castration-resistant prostate cancer (CRPC) progression." (PMID 32427840, 2020). "Throughout the entire natural history of prostate cancer, AR remains active and is still expressed in patients undergoing ADT." (PMID 32316460, 2020). "Androgen receptor (AR) signaling is known to be involved in the etiology and progression of BC, while the AR gene is a direct target of SMYD3 in prostate cancer." (PMID 32007952, 2020). "Reduced PMEPA1 (isoform -b) expression leads to up-regulated AR protein, activation of AR signaling, and subsequent accelerated prostate cancer cell growth." (PMID 32842649, 2020). "Of the genes that are jointly regulated by OCT1 and the AR in prostate cancer, acyl-CoA synthetase long-chain family member 3 (ACSL3) is the mostly highly differentially expressed." (PMID 33134178, 2020). "While the role of AR in prostate cancer is more completely understood, the importance of AR signaling in breast cancer is an area of increasing investigation." (PMID 33062889, 2020). "Taken together, our findings suggest a crucial role played by FUT8 as a mediator in switching prostate cancer cells from nuclear receptor signaling (androgen receptor) to the cell surface receptor (EGFR) mechanisms in escaping castration-induced cell death." (PMID 32085441, 2020). "The study was able to promote new perceptions on the function of IL-6 in AR activation in prostate cancer cells and as inhibited by resveratrol." (PMID 32961987, 2020). "In recurrent prostate cancer (PCa), treatment usually entails androgen withdrawal therapy using androgen receptor (AR) antagonists leading to suppression of androgen production." (PMID 32577155, 2020). "AMACR mRNA detected in cancer tissues increased by 682 times compared to normal tissue in patients with prostate cancer, and increased by 11.5 times for AR mRNA." (PMID 32760737, 2020). "Altogether, in addition to a benign stage, AR remains an important therapeutic target for advanced prostate cancer." (PMID 32093357, 2020). "Additional targeted therapies in prostate cancer include androgen-receptor (AR) targeting drugs such as abiraterone acetate, apalutamide, or enzalutamide as well as PARP-inhibitors in patients with DNA-repair defects." (PMID 32403427, 2020). "Androgen deprivation therapy targeting the androgens/androgen receptor (AR) signaling continues to be the mainstay treatment of advanced-stage prostate cancer." (PMID 35582225, 2020). "For example, although MPC inhibition drives cancer progression in most studies of prostate cancer, MPC deletion in models of androgen receptor-driven prostate cancer abolishes cell growth and is rescued by pyruvate supplementation." (PMID 32784379, 2020).
prostate carcinoma (continued). "The molecular characterization of AR mRNA in CTCs and the detection of AR-V7 in CTCs can be used as a tool to guide treatment decisions for men with advanced prostate cancer." (PMID 33333999, 2020). "A key finding from our study is that AR-driven alternatively spliced genes had a distinct physiological role from those that were transcriptionally regulated by AR in prostate cancer cells." (PMID 32820253, 2020). "For example, since androgen plays an important role in the progression of prostate cancer, AR antagonists have been used clinically for the treatment of prostate cancer." (PMID 32759847, 2020). "Prostate cancer (PCa) is initially driven by excessive androgen receptor (AR) signaling with androgen deprivation therapy (ADT) being a major therapeutic approach to its treatment." (PMID 32292603, 2020). "Intriguingly, W7 and TFP enhance apoptosis in prostate cancer cells by promoting AR proteolysis upon liberation from CaM." (PMID 31944520, 2020). "Nevertheless, the roles of other PMEPA1 isoforms (c, d and e) in the context of AR signaling were not fully understood in prostate cancer cells." (PMID 32064040, 2020). "The androgen receptor (AR) plays a key role in the tumorigenesis of prostate cancer and is thus an effective therapeutic target in prostate cancer." (PMID 32799866, 2020). "Most studies of androgen–AR complex-mediated gene expression have been carried out in the context of male reproductive tissue in prostate cancer (PCa)." (PMID 32849595, 2020). "Targeting the androgen receptor (AR) signalling pathway remains the main therapeutic option for advanced prostate cancer." (PMID 32459381, 2020). "Sublines have been established from PDXs of prostate cancer by maintaining them in testosterone-supplemented versus castrated host mice, providing useful models to study changes in AR signaling in castration-resistant prostate cancer." (PMID 33094211, 2020). "Taken together, our findings demonstrate that AR signaling negatively regulates SPINK1 expression and draws attention to AR antagonists mediated upregulation of SPINK1 in prostate cancer." (PMID 31959826, 2020). "The study revealed for the first time that stimulating human prostatic carcinoma cell line- fast growing colony (LNCaP-FGC) cells with IL-6 clearly induced the AR transcriptional activity while resveratrol reduced IL-6-induced AR activity." (PMID 32961987, 2020). "Finally, siRNA depletion of Twist1 in prostate cancer cells caused increased E-Cadherin expression and decreased N-Cadherin expression and the opposite effects on cell migration, mimicking what was observed with AR depletion, suggesting that the AR effect on EMT and migration are mediated by Twist1." (PMID 32296610, 2020). "This review will cover principally the development of agents to image the estrogen receptor (ER) and the progesterone receptor (PgR) in breast cancer and the androgen receptor (AR) in prostate cancer." (PMID 32718075, 2020). "The predictive and prognostic role of AR in prostate cancer is rather different than that of ER in breast cancer." (PMID 32718075, 2020). "The role of the androgen receptor to signal as a transcription factor has been well-characterized in prostate cancer and is increasingly being recognized and studied in breast cancer." (PMID 32117061, 2020). "AR is a key modulator of proliferation and progression of prostate cancer, which makes it an important target in prostate cancer chemoprevention and treatment." (PMID 31996731, 2020). "The oncogenic AR, hypoxia and HIF1a pathways support prostate cancer development through independent signaling pathways and transcriptomic profiles." (PMID 32450824, 2020). "We previously showed that AR co-immunoprecipitated with CHK2 immune complexes in several prostate cancer cell lines." (PMID 32579110, 2020).
prostate carcinoma (continued). "Earlier studies demonstrate that KDM5B is not only overexpressed in hormone-driven cancers such as the breast and prostate cancers, but also interacts with hormone receptors, ER and AR, to positively regulate their transcriptional activities." (PMID 33245716, 2020). "In prostate cancer cells HEY1 functions as a corepressor for AF1 in the AR, inhibiting transcription from androgen-dependent target genes." (PMID 33167316, 2020). "In prostate cancer, PTEN deletions are associated with abnormal induction of AKT–mTOR and androgen receptor (AR) signaling pathways." (PMID 32708484, 2020). "For instance, the co-culture of preadipocytes suppresses AR expression through the up-regulation of miR-301a expression in prostate cancer cells, resulting in the up-regulation of TGFβ1, Smad, and MMP9 expression for metastasis." (PMID 32971847, 2020). "The standard-of-care treatment for prostate cancer is androgen deprivation therapy (ADT) which results in inhibition of androgen receptor (AR) signaling pathway and efficiently controls the growth of androgen-dependent tumors." (PMID 32313004, 2020). "In conclusion, this study highlights the so-far undescribed role of AR in modulating gene expression via ASE in prostate cancer." (PMID 32820253, 2020). "Our work using prostate cancer cell lines showed that AR signaling dysregulates the splicing of functionally relevant genes." (PMID 32820253, 2020). "AR and hypoxia/HIF1a signaling pathways independently promote prostate cancer progression and therapeutic targeting of both pathways simultaneously is warranted." (PMID 32450824, 2020). "Given the critical roles of Tip60 in AR activation, and in various metabolic pathways, targeting Tip60 appears to be a promising therapeutic option for different stages of prostate cancer, including the androgen-independent stage." (PMID 32927797, 2020). "Although PCai1 cell growth was androgen-independent, increased AR expression was clearly observed compared to human prostate cancer cell lines." (PMID 32093357, 2020). "In the prostates of mice with inactivated ERβ, mutant phenotypes include epithelial hyperplasia and increased expression of androgen receptor (AR)-regulated genes, most of which are also upregulated in prostate cancer (PCa)." (PMID 32413024, 2020). "For instance, increased copy number of the enhancer 650 kb centromeric to androgen receptor (AR) gene is the key driver for aberrant activation of AR, and drives the metastasis of prostate cancer." (PMID 32941624, 2020). "For example, histone methyltransferase EZH2, a core unit of PRC2 complex, can play a PRC2-independent role by interacting with androgen receptor (AR) to activate a subset of its target genes in an androgen-independent prostate cancer cell line." (PMID 32093739, 2020). "Since patients’ prostate cancer cells are thought to overexpress the AR, one basic treatment for recurrent systemic disease, is breaking the Androgen-AR pathway." (PMID 32256979, 2020). "Abnormal expression of proteins such as PSA and AR has been used as a biomarker for the diagnosis or treatment of prostate cancer." (PMID 32066485, 2020). "MDM2 and c-terminus of HSP70-interacting protein (CHIP)-mediated ubiquitination induces AR degradation in prostate cancer." (PMID 31896509, 2020). "Upregulation of the androgen receptor is a well-known consequence of Akt activation in prostate cancer." (PMID 32417965, 2020). "The histone deacetylase 6 (HDAC6) mapped to Xp11.23 is an important AR regulator in prostatic cancer by enhancing AR protein stability." (PMID 32626651, 2020). "Recently, WDR5, a subunit of the SET1/MLL (mixed lineage leukemia) complex, has been suggested as a major driver of AR-dependent prostate cancer and has been shown to interact with H3T11P to guide MLL1 to the AR target gene site and promote H3K4me3." (PMID 32629770, 2020).
prostate carcinoma (continued). "We further show that Twist1 promotes EMT and migration of prostate cancer cells, and our data suggest that Twist1 plays an important role in mediating the AR induction of EMT and cell migration." (PMID 32296610, 2020). "The involvement of AR in modulation of differential gene transcription programming in both AR-dependent and AR-independent prostate cancer has also been reported." (PMID 32585812, 2020). "Here, we have leveraged next-generation sequencing and newly developed analytical methodologies to evaluate the role of AR signaling in regulating the transcriptome of prostate cancer cells." (PMID 32820253, 2020). "Here, we analyzed the expression patterns of two PCSC-associated membrane markers, CD44 and EpCAM, in 3D-cultured prostatospheroids derived from three different prostate cancer cell lines (AR-positive LNCaP and VCaP; AR-negative DU145)." (PMID 32183880, 2020). "A recent study uncovered a mechanism in which FKBP5 is found to form a complex with HSP90 and promote AR signaling in prostate cancer." (PMID 32316460, 2020). "Given the importance of the AR pathway in prostate cancer, it is the target of most treatments for advanced disease." (PMID 33134178, 2020). "Despite being the main target of hormonal therapies for over five decades, AR remains the key driver of prostate cancer progression to CRPC." (PMID 32427840, 2020). "Recently, overexpression or amplification of CREB5 was reported to promote proliferation and mediate resistance to AR inhibition in metastatic castration-resistant prostate cancers." (PMID 32843066, 2020). "Oral administration of carnosol reduced tumour growth, serum prostate specific antigen levels and decreased AR and ER-α protein expression in a xenograft model of prostate cancer." (PMID 33049974, 2020). "AR plays a vital role in the progression of prostate cancer and is a crucial target for therapeutic interventions." (PMID 32820253, 2020). "The mechanism of action underlying its anti-prostate cancer activity has been extensively explored, with the crosstalk between adenosine monophosphate-activated protein kinase (AMPK) activation and AR degradation as the most attractive one." (PMID 32456317, 2020). "Conversely, AR upregulates pathways in prostate cancer that increase genomic instability, such as the TMPRSS2-ERG gene fusion, which is present in a significant part of advanced prostate cancers." (PMID 32123273, 2020). "To select best reference controls for CN quantification at AR loci, we first examined existing databases to determine the relative stable genomic regions in prostate cancer." (PMID 32752286, 2020). "A growing amount of literature has demonstrated that AR overexpression is positively correlated with cancer progression and poor prognosis in prostate cancer and colorectal cancer." (PMID 32258155, 2020). "[18F]FES and [18F]FDHT uptake correlates well with ER and AR expression levels in breast and prostatic cancer." (PMID 32722205, 2020). "At diagnosis, most prostate cancers rely on the androgen receptor (AR) signaling for growth and survival." (PMID 33134178, 2020). "By blocking this interaction, D2 inhibits nuclear translocation of the AR and reduces the growth of prostate cancer cells." (PMID 33134178, 2020). "Induction of AR degradation or repression of AR-mediated transcription is a well-known strategy to inhibit tumor development in prostate cancer." (PMID 31896509, 2020). "Recent in vitro data have also revealed that mTOR can directly interact with AR in the nucleus of prostate cancer cells to promote metabolic rewiring, and high levels of nuclear mTOR correlate with poor prognosis in patients with prostate cancer." (PMID 32630372, 2020). "As expected, the levels of AR mRNA and protein in bladder cancer cells were quite low compared to that in LNCaP prostate cancer cells." (PMID 32781788, 2020).
prostate carcinoma (continued). "We tested 112 well-characterized RBPs and found that expression of ESRP1/2 in prostate cancer cells decreased in response to treatment by pharmacological inhibitors of AR." (PMID 32820253, 2020). "Increased AR activity can drive therapeutic resistance in advanced prostate cancer, rendering several novel therapeutics ineffective." (PMID 32752286, 2020). "Increasing knowledge of the subject has provided information that prostate cancer is a heterogeneous disease with the coexistence of both AR-responsive and AR-refractory cancer cells responsible for antiandrogen resistance at various degrees." (PMID 35582225, 2020). "MiR-30 family members are some of the most prominent in prostate cancer cells that can directly target AR." (PMID 32645914, 2020). "It is worth emphasizing that androgen receptor (AR) has been expressed in both prostate cancer cells but in PC3 line is many times lower than in LNCaP." (PMID 32872192, 2020). "A search of PubMed, Embase, and the Web of Science was performed using the keywords prostate cancer, prostate tumor, prostate neoplasm, prostate carcinoma; AR-V7, AR3, androgen receptor splicing variant-7, or androgen receptor-3." (PMID 32390764, 2020). "Nevertheless, in prostate cancer, AR binds to the PTEN promoter as a repressor, thereby inhibiting its transcription." (PMID 32982970, 2020). "A recently published paper from our research group described the H3K27 demethylase activity of KDM7A on the response elements of AR target genes in prostate cancer." (PMID 32781788, 2020). "In prostate cancer, the androgen receptor (AR)-signaling pathway is key in regulating disease progression, and is a major target for therapeutic intervention." (PMID 31941153, 2020). "Enzalutamide is a second-generation AR antagonist approved for castration-resistant prostate cancer patients." (PMID 31952272, 2020). "EPSTI1 for breast cancer, AR for prostate cancer, GRAP for oral squamous cell carcinoma, CDCP1 and PLAGL2 for ovarian cancer were the only five direct targets identified for miR‐654‐5p thus far." (PMID 33135351, 2020). "In LNCaP prostate cancer cells, androgens work through the androgen receptor to regulate both PSA mRNA and glycoprotein levels." (PMID 32872551, 2020). "Consistent with these gene expression changes, Twist1 depletion strongly repressed the migration of prostate cancer cells, comparable in effect to AR knockdown." (PMID 32296610, 2020). "Meanwhile, it was reported that SRSF1 regulates splicing of AR pre-mRNA to generate AR-V7 in prostate cancer." (PMID 32106418, 2020). "A low expression in bladder cancer stem cells (lncRNA LBCS) forms a complex with the RNA-binding protein hnRNPK and androgen receptor (AR) mRNA to suppress AR translation in prostate cancer." (PMID 32429086, 2020). "The development of prostate cancer (PCa) is initially driven by androgen steroid hormones via the androgen receptor (AR) transcription factor." (PMID 32522053, 2020). "As African American (AA) men often carry the wild type CYP3A5 and express high levels of CYP3A5 protein, we blocked the wild type CYP3A5 in AA origin prostate cancer cells and tested its effect on androgen receptor signaling." (PMID 32316460, 2020). "In another research, it has been demonstrated that PLGA-curcumin nanoparticles enhanced the lysosomal activity, apoptosis, inhibition of androgen receptor (AR), and nuclear β-catenin activity that resulted from a growth obstruction in prostate cancer cells." (PMID 32425772, 2020). "Androgen signaling via the Androgen Receptor (AR) drives the development and progression of prostate cancer." (PMID 32296610, 2020). "We showed that endothelial cells-derived FGF2 can induce ERG expression in prostate cancer cells in an AR-independent manner." (PMID 33425737, 2020). "Taken together, the recent clinical data from studies exploring AKT inhibitors in prostate cancer is promising, particularly in combination with androgen/AR blockade." (PMID 33105713, 2020).